FCER2 (Fc epsilon receptor II)
Description:
Low-affinity receptor for immunoglobulin E (IgE) and CR2/CD21. Has essential roles in the regulation of IgE production and in the differentiation of B cells. On B cells, initiates IgE-dependent antigen uptake and presentation to T cells. On macrophages, upon IgE binding and antigen cross-linking induces intracellular killing of parasites through activation of L-Arginine-nitric oxide pathway.
Synonyms: CD23; CD23A; CLEC4J; FCE2; IGEBF; FCErII; FcepsilonRII; BLAST-2
Tractability: Small molecule: it belongs to a druggable protein family. Antibody: a drug acting on it is in phase 2 or 3 trials; UniProt places it where antibodies can reach, with high confidence; its Gene Ontology location is reachable by antibodies, with high confidence; UniProt predicts a signal peptide or a membrane-spanning region. PROTAC: a small molecule that binds it is known.
Target class: Membrane receptor
Gene: Protein-coding gene on chromosome 19 (7,688,758 to 7,702,146, reverse strand). Ensembl gene ENSG00000104921.
Subcellular location: Cell membrane; Secreted
Pathways (Reactome):
Immune System: Interleukin-10 signaling; Interleukin-4 and Interleukin-13 signaling
Signal Transduction: NOTCH2 intracellular domain regulates transcription
Gene Ontology:
Molecular function: IgE binding; low-affinity IgE receptor activity; protease binding; protein binding; carbohydrate binding; integrin binding; pattern recognition receptor activity
Biological process: B cell antigen processing and presentation; defense response to bacterium; Fc receptor-mediated immune complex endocytosis; Fc-gamma receptor signaling pathway involved in phagocytosis; macrophage activation; positive regulation of gene expression; immune response; Fc-epsilon receptor signaling pathway
Cellular component: extracellular exosome; extracellular region; plasma membrane; external side of plasma membrane
Genetic constraint (gnomAD): Loss-of-function variants: 35 observed, 42.7 expected, observed/expected ratio (o/e) 0.82, 90% interval 0.62 to 1.09. The upper end of that interval is the gene's LOEUF score, 1.09, which puts it in group 4 of 6, group 1 being the genes least tolerant of losing a copy. Missense variants: 410 observed, 405.57 expected, observed/expected ratio (o/e) 1.01, 90% interval 0.93 to 1.1. Synonymous variants: 159 observed, 163.04 expected, observed/expected ratio (o/e) 0.98, 90% interval 0.86 to 1.11.
Homologues: Orthologues: chimpanzee FCER2 (99% identical), macaque FCER2 (88% identical), rabbit FCER2 (62% identical), dog FCER2 (58% identical), rat Fcer2 (56% identical), mouse Fcer2a (56% identical), Drosophila melanogaster tfc (17% identical), tropical clawed frog clec4m (17% identical), tropical clawed frog asgr1 (15% identical), tropical clawed frog clec4e (15% identical), zebrafish asgr1c.2 (15% identical), zebrafish asgr1b (14% identical), and 15 more. Paralogues in human: CD207 (21% identical), ASGR1 (20% identical), ASGR2 (20% identical), CLEC4F (19% identical), CLEC10A (18% identical), CLEC4M (18% identical), CD209 (18% identical), CLEC17A (17% identical), CLEC4G (17% identical), CLEC4A (15% identical), CLEC4E (15% identical), CLEC4C (14% identical), and 2 more.
Diseases named in the same sentence as FCER2 in open-access papers:
FCER2 is named in the same sentence as 154 diseases in open-access papers, as found by Europe PMC text mining. Sharing a sentence is not in itself a finding about the gene and the disease. The quoted sentences say what the papers report.
Chronic lymphocytic leukemia (114 papers, 2003 to 2026). "FCER2 (CD23) surface expression is mutually exclusive in chronic lymphocytic leukemia (CLL)." (PMID 34035992, 2021).
Allergy (37 papers, 2012 to 2026). An allergy is an immune response or reaction to substances that are usually not harmful. "Among these, the gene for the low-affinity receptor for IgE (FCER2) has been implicated as a candidate for IgE-mediated allergic diseases and bronchial hyper-reactivity." (PMID 36496569, 2022). "On the basis of study with animal models, FCER2 has been implicated in IgE-mediated allergic diseases and bronchial hyper-reactivity." (PMID 28302172, 2017). "FCER2, however, codes for a low-affinity immunoglobulin E receptor involved in allergy and resistance to parasites." (PMID 23424103, 2013).
asthma (32 papers, 2005 to 2024). "The FCER2 gene encodes a low affinity IgE receptor, and a new variant (rs28364072) can increase the severity of asthma after using glucocorticoids, which has been identified by Childhood Asthma Management Program, as demonstrated in children." (PMID 29751569, 2018). "It has been proved that FCER2 is involved in the pharmacogenetic basis for severe exacerbations in children with asthma." (PMID 28302172, 2017).
leukemia (13 papers, 2011 to 2025). A malignant (clonal) hematologic disorder, involving hematopoietic stem cells and characterized by the presence of primitive or atypical myeloid or lymphoid cells in the bone marrow and the blood. "The genes in the leukemia cell line term were AFDN (alias MLLT4, chromosome 1, WHWT), KLF3 (chromosome 3, LR), RPS6, (chromosome 5, LR), and FCER2, MCOLN1, and PRAM1 on chromosome 20 (GSD)." (PMID 36482174, 2022).
sarcoma (7 papers, 2011 to 2022). A usually aggressive malignant neoplasm of the soft tissue or bone. "Increased levels of the Fc fragment of IgE receptor II (FCER2) have been implicated in different hematological malignancies and sarcomas." (PMID 35267445, 2022).
COVID-19 (5 papers, 2020 to 2024). A disease caused by infection with severe acute respiratory syndrome coronavirus 2. "Out of 22 eligible articles that investigated candidate genes (2 as associated with COVID-19), the top-ranked genes in the number of studies were ACE2, CLEC4M (L-SIGN), MBL, MxA (n = 3), ACE, CD209, FCER2, OAS-1, TLR4, TNF-α (n = 2)." (PMID 32917282, 2020). "In addition to activation of plasma-related pathways, we also observed in naïve B cells that FCER2 was downregulated while SLAMF7 was upregulated suggesting significant activation of these cells in COVID-19." (PMID 37848421, 2023).
colorectal cancer (4 papers, 2020 to 2025). A primary or metastatic malignant neoplasm that affects the colon or rectum. "The results showed that, compared with normal tissues, the expression of ADRA1B, CDKN2A, FCER2, and IL13 was significantly upregulated in colorectal cancer tissues, while CALM1, CTNNA1, GSR, INSR, and MAPK9 were significantly downregulated." (PMID 40696679, 2025).
Sepsis (4 papers, 2016 to 2025). Sepsis is defined as life-threatening organ dysfunction caused by a dysregulated host response to infection. "In summary, our research has identified twelve genes, including CD3E, CD40LG, LILRA5, and FCER2, as potential diagnostic markers for sepsis." (PMID 40129981, 2025). "By revealing a causal link between sepsis and CFHR5, FCER2, GZMB, HLA-DQA2, MBL2, or MPO, our study offers an essential resource for additional investigations on the subject." (PMID 39252215, 2024). "Moreover, in the GSE137340 validation group, the levels of CD3E, CD40LG, FCER2, and P2RY10 expressions were markedly reduced in the sepsis group when contrasted with the control group (P < 0.05)." (PMID 40129981, 2025).
pneumonia (3 papers, 2021 to 2025). An acute, acute and chronic, or chronic inflammation focally or diffusely affecting the lung parenchyma, caused by an infection in one or both of the lungs (by bacteria, viruses, fungi, or mycoplasma.). "Research indicates that the BL13 acupoint modulates pneumonia by targeting multiple genes, such as FCER2, IL4R, FASLG, and others, to modulate cytokine signaling in the immune system." (PMID 40098935, 2025).
nasopharyngeal carcinoma (2 papers, 2020 to 2024). A carcinoma arising from the nasopharyngeal epithelium. "In a nasopharyngeal carcinoma study, it was found that FCER2 was a downregulated gene in nasopharyngeal carcinoma, and its expression levels were significantly lower in nasopharyngeal carcinoma than in adjacent tissues." (PMID 38562021, 2024).
psoriasis (2 papers, 2017 to 2023). An autoimmune condition characterized by red, well-delineated plaques with silvery scales that are usually on the extensor surfaces and scalp. "Only B6 mice, for example, showed significantly decreased expression of Fcer2, Cspg4, Lsp1, and Aldh1b1 with IMQ treatment to recapitulate expression shifts unique to psoriasis lesions." (PMID 28279190, 2017).
gastric cancer (1 paper, 2012). A primary or metastatic malignant neoplasm involving the stomach. "Nine human RNAs were significantly upregulated in EBV-infected compared to EBV negative gastric cancers: FCER2, MS4A1 (CD20), PLUNC, TNFSF9, TRAF1, CXCL11, IFITM1, PPARG, and FCRL3.." (PMID 22929309, 2012).
muscle tumors (1 paper, 2023). "In addition, 25 DPs are related to muscle tumors; 8 DPs (APOE, FCER1A, FCER2, GSK3B, HSPD1, IL6R, MMP7, and RARRES2) are linked to proliferation of muscle cells." (PMID 36918772, 2023).
prostate adenocarcinoma (1 paper, 2022). "In addition, FCER2 is expressed in subsets of B cells and in particular depicts follicular dendritic cell networks, whereas expression changes in urine could reflect an altered immune microenvironment in prostate adenocarcinoma patients." (PMID 35267445, 2022).
prostate carcinoma (1 paper, 2024). A carcinoma that arises from epithelial cells of the prostate gland. "Another study reported that the expression of FCER2 was significantly decreased in prostate cancer, which could serve as a reliable biomarker to avoid unnecessary prostate biopsies and misdiagnosis." (PMID 38562021, 2024).
sarcoidosis (1 paper, 2024). Sarcoidosis is a multisystemic disorder of unknown cause characterized by the formation of immune granulomas in involved organs. "(e) Finally, sarcoidosis-associated B cells expressed MS4A1 (also known as CD20), FCER2 (also known as CD23), BCL6, and AICDA, which are all markers of late-stage differentiated B cells in mature TLSs." (PMID 39225100, 2024).
scleroderma (1 paper, 2021). Scleroderma is a rare autoimmune connective tissue disorder characterized by abnormal hardening of the skin and, sometimes, other organs. "We note 38 of the genes found expressed in T cells TADs encompassing the scleroderma associated SNPs were also found to be differentially expressed in Dolcino’s study, including BSG, FCER2, GPA33, MAP2K7, SCAMP2, and TSPAN33." (PMID 33894768, 2021).
tumor (109 papers, 2005 to 2026). "In addition, FCER2 was significantly associated with individual cancer stages, and the expression of FCER2 decreases with tumor progression." (PMID 38562021, 2024). "Consistent with the previous studies, these findings suggested that the FCER2 may participate in the progress of HCC as a tumor suppressor gene." (PMID 38562021, 2024). "FCER2 + B cells inhibit tumor proliferation and migration in vitro." (PMID 37828063, 2023). "We also found FCER2 to be a potential tumor-suppressing B-cell surface marker." (PMID 37828063, 2023). "FCER2+ B cells might inhibit tumor proliferation and migration." (PMID 37828063, 2023). "In addition, FCER2, CD200R1, and RHOV in the signature were strongly associated with the clinical stage of the tumor, and univariate cox analysis showed that except for TNNT2, WT1 and KRTAP5-8, the remaining signature genes were closely correlated with the prognosis of LUAD patients." (PMID 37234773, 2023). "Most B lymphocytes were derived from the PPLELC tumor and defined into three subsets: plasma (SDC1), follicular B cells (FCER2) and germinal centre (GC) B cells (BCL6)." (PMID 40057671, 2025). "Therefore, in terms of regulating the tumor microenvironment, ADRB2, SMAD4, FCER2 and PDCD1 had vital predictive significance in the immunotherapy of NSCLC." (PMID 36005189, 2022). "However, the expression of CLEC4A, CLEC4D, CLEC4E, CLEC4J (FCER2), CLEC4K (CD207), CLEC4G, CLEC4H1, CLEC4M, and CLEC4H2 decreased with tumor progression." (PMID 34409028, 2021).
infection (30 papers, 2009 to 2026). The state of being infected such as from the introduction of a foreign agent such as serum, vaccine, antigenic substance or organism. "The upregulation of genes encoding B cell surface molecules—including CD19, MS4A1, CD22, FCER2, and CR1—may be involved in the proliferation and differentiation of memory B cells induced by the vaccine doses, following BA.5 infection." (PMID 39499071, 2024).
cancer (16 papers, 2012 to 2025). A tumor composed of atypical neoplastic, often pleomorphic cells that invade other tissues. "Although existing research on FCER2 predominantly focuses on cancer, it is hypothesized that FCER2 plays a role in the regulation of ovarian aging." (PMID 38352714, 2024). "Compared to uninfected cancers, the infected cancers had significant upregulation of nine cellular factors (FCER2, MS4A1 (CD20), PLUNC, TNFSF9, TRAF1, CXCL11, IFITM1, PPARG, and FCRL3), implying that EBV is not an innocent bystander with respect to biochemical impact." (PMID 22929309, 2012). "Previous studies also showed that the expression of certain TSGs could promote antitumor immunity in diverse cancers, such as CCL21, MADCAM1, and FCER2." (PMID 32774369, 2020).
inflammation (2 papers, 2017 to 2022). Aberrant reaction of the microcirculation characterized by movement of fluid and leukocytes from the blood into extravascular tissues. "Therefore, further study will be needed to prove that up-regulated FCER2 causes the bronchial inflammation and hyper-immune reactivity." (PMID 28302172, 2017).
cardiovascular disease (1 paper, 2022). "FCER2, a B-cell specific antigen involved in the inflammatory response, is associated with cardiovascular disease." (PMID 36078037, 2022). "Among these genes, TYW1B, FCER2, SELE, and SDC-1 had some degree of connection with cardiovascular diseases including AF." (PMID 36078037, 2022).
FCER2 also shares sentences with these, for which no sentence is quoted: lymphoma (32 papers); mantle cell lymphoma (30); follicular lymphoma (27); MALT lymphoma (14); B-cell lymphoma (13); allergic asthma (8); melanoma (8); malaria (7); follicular dendritic cell sarcoma (6); systemic lupus erythematosus (6); food allergy (5); marginal zone lymphoma (5); AIDS (4); Burkitt lymphoma (4); diffuse large B-cell lymphoma (4); lymphoproliferative disorders (4); myeloma (4); rheumatoid arthritis (4); Arthritis (3); atopic dermatitis (3); autism (3); autoimmune disease (3); Autoimmunity (3); colitis (3); hairy cell leukemia (3); airway allergies (2); allergic rhinitis (2); anaphylaxis (2); Castleman disease (2); chronic idiopathic urticaria (2).
A further 102 diseases each share a sentence with FCER2 in 2 papers or fewer.